IFNG (interferon gamma)
Diseases named in the same sentence as IFNG in open-access papers (continued):
Sharing a sentence is not in itself a finding about the gene and the disease.
psoriasis (518 papers, 2006 to 2026). An autoimmune condition characterized by red, well-delineated plaques with silvery scales that are usually on the extensor surfaces and scalp. "JAK/STAT disruption has been associated with psoriasis through the high expression of pathogenic mediators, such as Th1 cytokine interferon gamma (IFN-γ), contributing to the expression of genes involved in chronic inflammation." (PMID 40725772, 2025). "The production of tumor necrosis factor-alpha (TNFα), interferon-gamma (IFNγ), and IL-8 is promoted around this IL-23/IL-17 A system, which is thought to cause a chain reaction of psoriasis exacerbations." (PMID 40481552, 2025). "This activation initiate differentiation of Th22 and Th17 cell subsets, result in generation of a cascade of psoriasis-associated cytokines including interferon-gamma (IFN-γ), TNF-α, IL-22, and IL-17." (PMID 40818978, 2025). "Here, IFNγ and TNFα, the key Th1 cytokines implicated in psoriasis pathogenesis, induced SULT2B1 expression in human epidermal KCs, whereas Th2 and Th17 cytokines did not alter SULT2B1 expression." (PMID 41181147, 2025). "Cross-talk between the innate and adaptive immune systems mediated by tumor necrosis factor-alpha (TNF-α) and interferon-gamma (IFN-γ) has also been implicated in the pathogenesis of psoriasis." (PMID 35805960, 2022). "During psoriasis, keratinocytes attract T cells by releasing chemokines, while skin-infiltrating self-reactive T cells secrete proinflammatory cytokines, e.g., IFNγ and IL-17A, that cause epidermal hyperplasia." (PMID 31324882, 2020). "mRNA from other proinflammatory cytokines associated with psoriasis pathogenesis, IFNG, TNFA and IL-1 family members IL1B and IL36A were also markedly elevated in psoriatic lesional skin." (PMID 28790368, 2017). "Culture of dermal ECs with psoriatic cytokines (such as IFNγ, IL-17, and TNFα) also induced expression of many of the same chemokines found upregulated after transfection of ECs with psoriasis-associated CARD14 mutations." (PMID 25369198, 2014). "Additionally, circulating CD8 T cells predominantly respond with IFNγ production in patients with the HLA-Cw6 allele, which is associated with early-onset psoriasis." (PMID 40391222, 2025). "To further determine the impact of mPGES-1 on the developing T-cell immunologic responses associated with psoriasis, after inducing psoriasis, we determined the fraction of αβ T cells and γδ T cells producing IL-17 A and IFNγ in the skin cells of mPGES-1−/− and WT mice." (PMID 40481552, 2025). "This response is magnified by priming with psoriasis-associated cytokines, IL-17A and IFNγ." (PMID 40121229, 2025). "IFNγ has been implicated in chronic inflammatory diseases such as psoriasis." (PMID 40637163, 2025). "Using a humanized mouse model of psoriasis, transplantation of unaffected skin from a patient with psoriasis was grafted onto mice deficient in type I and type II interferons and the recombination activating gene 2, (IFNG-/- IFNAR-/- RAG2-/-) and the skin graft spontaneously developed psoriasis." (PMID 34012438, 2021). "Likewise, another inflammatory cytokine associated with psoriasis, interferon gamma, has been shown to suppress CREB, MITF, p38 MAPK and melanogenesis." (PMID 34884858, 2021). "Finally, we demonstrate that the product of the plasma levels of IFNγ and TNFα associate with the presence of early coronary artery disease burden in patients with psoriasis." (PMID 32646751, 2020). "However, overall psoriasis-associated genes and genes belonging to signaling pathways of IL-22, IFNγ, TNFα, IL-1, and IL-17 were more strongly suppressed by ustekinumab than by etanercept." (PMID 31673756, 2019). "Additionally, HDBECs cultured with IL-17, TNFα, and IFNγ, three cytokines heavily implicated in psoriasis pathogenesis, resulted in upregulation of IL-8, CXCL1, CXCL10, and CCL5." (PMID 25369198, 2014).
psoriasis (continued). "DS patients exhibit elevated interferon-gamma levels and type 1 T-helper (Th1) cells, creating a proinflammatory milieu that sustains a positive feedback loop, perpetuating psoriasis." (PMID 40717838, 2025). "Dermal M1 and M2 MACs play an important role in developing and maintaining several chronic immunodermatoses such as atopic dermatitis and psoriasis notably driven by the potent, pro-inflammatory cytokine IFNγ." (PMID 40869132, 2025). "IL-17A is the key driver of the pro-inflammatory keratinocyte pathogenesis in psoriasis, along with a dominant IFNγ/STAT1 signature." (PMID 39843435, 2025). "To this end, we first examined the expression of IL1B, IL17, IL22 and IFNG, all well-known cytokines involved in the pathogenesis of psoriasis, in the scRNAseq dataset." (PMID 40746860, 2025). "An in vitro investigation simulating psoriasis-like cytokine-driven inflammation subjected cultured CD1d-expressing keratinocytes to interferon-gamma alongside α-galactosylceramide, a glycolipid antigen from the lectin family, to evaluate immune activation." (PMID 40690118, 2025). "Through these receptors, estrogen can downregulate the production of pro-inflammatory cytokines, such as tumor necrosis factor-alpha (TNF-α), interleukin-6 (IL-6), and interferon-gamma (IFN-γ), all of which are central to the pathogenesis of psoriasis." (PMID 39860587, 2025). "Using a cytokine cocktail containing IL-17A, interferon-gamma and tumour necrosis factor-alpha to produce a psoriasis-like phenotype, a role for ALOX15B in human epidermal keratinocyte inflammation was investigated." (PMID 39843435, 2025). "IFNγ plays a significant role in the pathogenesis of psoriasis, as it is often found elevated in both serum and lesional skin of affected patients." (PMID 40391222, 2025). "CD49a expression functionally delineates distinct subsets of TRMs, and in psoriasis, CD49a+ TRMs have the capacity to co-produce IFNγ and IL-17." (PMID 38892277, 2024). "Injection of IL-27 into psoriasis mice upregulated serum levels of IFNγ and decreased serum levels of IL-17, but inhibition of IL-27 downregulated the expression of IFNγ and increased IL-17 expression." (PMID 38566992, 2024). "CD8+ T cells residing in the epidermis and expressing both IFNγ and IL-17 have been indicated as key players in the autoimmune response in psoriasis patients as they are present at the site of disease recurrence." (PMID 37953417, 2024). "According to recent studies, elevated levels of tumor necrosis factor alpha; interleukins 1, 2, 10, 1 beta, 6 and 8; prostaglandin E2 and interferon gamma are suggested to be present in both psoriasis and depression." (PMID 38892934, 2024). "We determined susceptibility of KC to VV and HSV-1 infection after exposure to representative cytokines prevalent in diverse inflammatory cutaneous diseases: IFNγ (lupus/AD; type 1), IL-4 and IL-13 (AD; type 2), IL-22 and IL-17A (psoriasis/AD, type 3)." (PMID 37298195, 2023). "Samples from ichthyosis patients displayed an increase of general inflammatory (IL-2), innate (IL-1β), and some Th 1/interferon gamma (IFN-γ) markers that were comparable with psoriasis or atopic dermatitis." (PMID 38027029, 2023). "The activated JNK pathway in keratinocytes can mediate the recruitment of immune cells in psoriasis by regulating the production of inflammatory cytokines/chemokines, such as IL-6, IL-8, IL-23, IFNγ and TNFα, and CCL20 and hβD-2." (PMID 38008779, 2023). "Next, we compared the phenotypes of IFNγ-producing or IL-22-producing CD1a-reactive T cells from healthy and psoriasis." (PMID 37267382, 2023). "Another research found that intradermal administration of IFNγ-preconditioned EVs from UC-MSCs in mice (150 μg) can also reduce the symptoms of psoriasis described previously." (PMID 36891306, 2023).
psoriasis (continued). "IL-18 plays a major role in the induction of interferon-gamma signaling, and an increase in circulating IL-18 has been demonstrated in numerous inflammatory disease states including metabolic syndromes, psoriasis, and IBD." (PMID 37170273, 2023). "Cells within a single CD8 TEM cluster enriched among PSO subjects (cluster 11) showed a strong upregulation of CCL4, a CD8+ T cell recruiting chemokine associated with psoriasis, along with other inflammatory cytokines and chemokines (TNF, IFNG, CCL3, CCL4L2)." (PMID 35309349, 2022). "We found IFNγ-sEVs loaded with ASO-210 showed a stronger protective effect against psoriasis than the same amount of ASO-210 given separately with IFNγ-sEVs." (PMID 35359454, 2022). "IFNγ-sEVs accumulated in the injured skin and alleviated psoriasis symptoms, reduced dermal thickness, and inhibited proliferation of keratinocytes." (PMID 35359454, 2022). "The increased production of IL-17A and IFNγ in the supernatant of PS+T was also validated, confirming the evidence of the pro-inflammatory microenvironment specific of psoriasis." (PMID 36139479, 2022). "In other studies, examination of the effect of curcumin on PBMC of psoriasis patients showed reduced T cell proliferation and production of cytokines, such as IFNγ, IL-17, GM-CSF and IL-22." (PMID 36613560, 2022). "First, the accumulation of the drug-loaded sEVs in skin lesions led to the accumulation of drugs at high concentrations in the psoriasis region, which likely contributed to the prominent therapeutic effects of the drug-loaded IFNγ-sEVs." (PMID 35359454, 2022). "As cytokines represent important drivers of tissue inflammation in ncISD, we examined the expression of the major effector cytokines driving the common ncISD LP, AD, and psoriasis namely IFNG, IL13 and IL17A, respectively, in spatial resolution." (PMID 36513651, 2022). "These entities include IL-17, which is targeted by several biological therapeutics used in psoriasis, and IFNγ." (PMID 34877506, 2021). "The subcutaneous IFNγ injection led to the development of psoriasis-like lesions, which suggested a potential role of IFNγ in the pathophysiology of the disease." (PMID 31973112, 2020). "Of note, the previous attempts to use IFNγ+ CD3+/CD4+ T cell lines to induce psoriasis using this experimental approach were unsuccessful." (PMID 32153574, 2020). "To date, no prospective study has addressed the role of MTX therapy on tuberculin skin test (TST) or interferon-gamma release assay (IGRA) results among psoriasis patients living in TB-endemic areas." (PMID 33270676, 2020). "Psoriasis was initially thought to be a IFNγ related disease but more recent studies—and the success of biologics targeting the IL-17 pathway—indicate a more dominant role for TNFα and IL-17 driven disease." (PMID 32153574, 2020). "In human keratinocyte cultures activated with psoriasis-relevant proinflammatory cytokines, tofacitinib suppressed expression of IFNγ-dependent inflammatory genes and normalized keratinocyte responses." (PMID 31649667, 2019). "In psoriasis, a combination of the inflammatory cytokines IL-17, TNFα, IL-22, and IFNγ drives keratinocyte hyperproliferation and cytokine and chemokine release." (PMID 31673756, 2019). "The combined JAK1/TYK2 inhibitor, SAR-20347, demonstrated in vitro and in vivo concentration-dependent reduction of IL-12, IL-22, and IFNγ-mediated inflammation and tissue pathology in the imiquimod-induced psoriasis model." (PMID 31649667, 2019). "The composition of the inflammatory infiltrate (T cells, macrophages, dendritic cells and neutrophilic granulocytes) as well as inflammatory mediators (IFNγ, IL-12, IL-6, IL-17) are conspicuously similar in psoriasis and Crohn's disease." (PMID 31402919, 2019). "Upon contact with these autoreactive T cells in the skin, KRT17 peptides stimulate T cell proliferation and IFNγ production in psoriasis." (PMID 31374826, 2019).
psoriasis (continued). "Our preliminary data showed that Apremilast, a phosphodiesterase-4(PDE-4) inhibitor, used in the treatment of PsA and psoriasis (Ps) increased IL-10-producing Bregs and reduced IFNγ+CD3+ T cells and IL-17+CD3+ T cells." (PMID 32185301, 2018). "The effects of carnosol and curcumin on pro-inflammatory cytokine production by psoriasis PBMC was confirmed by analysis of IFNγ and IL-17 concentrations in cell culture supernatants by ELISA." (PMID 29980703, 2018). "IFNγ has also been shown to induce an inflammatory phenotype characteristic of psoriasis when injected into the skin and serum levels correlate with disease severity." (PMID 29535706, 2018). "Psoriasis patients have markedly elevated T-cell cytokines, including IFNγ, that correlate with elevated ACKR2 in unaffected skin." (PMID 29279330, 2018). "Our results demonstrate that curcumin effectively inhibited proliferation and production of IFNγ, IL-17, GM-CSF and IL-22 by T cells in ex-vivo stimulated psoriasis PBMC." (PMID 29980703, 2018). "Other pro-inflammatory cytokines such as IFNγ and GM-CSF have been described to contribute to the pro-inflammatory loop in psoriasis, while IL-22 directly stimulates keratinocyte proliferation." (PMID 29980703, 2018). "Among the investigated key cytokines relevant in psoriasis, IFNγ was detected as the main inducing factor for inflammatory caspase-5 besides caspase-1 in keratinocytes, whereas IL-17A had an amplifying effect." (PMID 28422993, 2017). "Psoriasis is a chronic inflammatory skin disease characterized by increased infiltration of IFNγ-producing Th1 cells as well as IL-17A-producing Th17 cells in the lesional plaques." (PMID 28472186, 2017). "Both psoriasis and IBD are Th1-mediated inflammatory disorders associated with enhanced synthesis of cytokines, TNF-alpha and interferon-gamma (IFN-gamma)." (PMID 28905102, 2017). "Although parts of the literature are conflicting, there is evidence that circulating levels of TNFα (in addition to IFNγ, IL-12) are elevated in psoriasis and correlate with disease severity." (PMID 26573299, 2016). "In psoriasis, T-cells (both CD4+ and CD8+) are known to cause low production of Th2 cytokines (IFNγ, TNFα, and IL-2) and high production of Th1 cytokines (IL-4, IL-6 and IL-10), leading to polarization of the type 1 pathway." (PMID 26849645, 2016). "The GO term “response to interferon-gamma” (GO:0034341) is also significantly enriched in psoriasis (FDR p = 1.9 × 10−3)." (PMID 25574825, 2015). "The cytokines produced by these cells, such as tumor necrosis factor-α (TNFα), interferon-γ (IFNγ), IL-17, IL-22, IL-23, IL-12 and IL-1β, create an inflammatory cascade, contributing to the pathogenesis of psoriasis." (PMID 24386404, 2013). "Of particular interest are cytokines involved in Th1 and Th17 biology (IL-12, IFNg, IL-23, IL-17A and IL-17F), which have been shown to play a role in psoriasis." (PMID 23308107, 2013). "IL18 also stimulates IFNγ production, and the presence of polymorphisms in the IL18 gene (rs187238) was associated with susceptibility to psoriasis in Japanese patients." (PMID 24069534, 2013). "Th1 cells have previously been considered to be significantly involved in psoriasis because of the large number of interferon-gamma- (IFN-γ-) producing cells observed in areas of cutaneous eruptions." (PMID 22545055, 2012). "For example, IL-17 and IFNγ synergistically induce β-defensin expression in patients with psoriasis and Th1-type chemokine production in patients with cancer." (PMID 22176654, 2011). "The function of the inflammatory processes that induce the migration of interferon gamma-producing Th1 lymphocytes into the skin is thought to be central to the development of psoriasis." (PMID 19309513, 2009). "Psoriasis is a T-cell-mediated disorder and the production of proinflammatory cytokines like Interferon-gamma (IFN-gamma), Interleukin-1 and Interleukin-12 plays an important role in the psoriatic phenotype." (PMID 17986321, 2007).
psoriasis (continued). "Thus, we aimed to analyze the mRNA expression of major cytokines, including IL-17 A, TNFα, and IFNγ in the skin of the IMQ-induced psoriasis pathological model." (PMID 40481552, 2025). "Similarly, effector CD8 T cells showed a significantly lower CD69 and IFNγ expression in psoriasis patients." (PMID 40391222, 2025). "Moreover, treatment with a cocktail of cytokines (IL-17A, IFNγ, TNFα) to induce a psoriasis-like phenotype in keratinocytes, increased ALOX15B RNA and protein expression." (PMID 39843435, 2025). "Notably, the module score also incorporated proinflammatory cytokines (IL17A, IL1B, IL22, IL23, and IFNG) which were upregulated in lesional psoriasis, providing context for the regulation of plakin family members." (PMID 40746860, 2025). "Despite being underpowered, as 4 out of 6 psoriasis subjects displayed positive enrichment scores for IFNγ in unadjusted analyses, we believe IFNγ production could be highly donor specific and/or disease activity‐dependent." (PMID 40926620, 2025). "GSVA revealed MC IL‐4 + IL‐13 signatures enriched in atopic dermatitis and psoriasis, IFNγ in COVID‐19 infection and cystic fibrosis, IL‐33 in COVID‐19 and chronic obstructive pulmonary disease (COPD) and TGFβ in pulmonary fibrosis (PF) and chronic rhinosinusitis." (PMID 40926620, 2025). "The frequency of CD69+, Granzyme B+ and IFNγ+ CD8 T cells in psoriasis patients was significantly lower following anti-CD3/CD28 stimulation (p<0.0005), suggesting downregulated TCR-dependent activation and impaired Tc1 cytokine production in CD8 T cells from psoriasis patients." (PMID 40391222, 2025). "Additionally, we identified distinct T cell expression patterns across disease states, including characteristic expression of IL13 and IL22 in AD, IL17 family genes in psoriasis, and IFNG in granuloma annulare (GA)." (PMID 40537825, 2025). "In addition, IL-6 release is further enhanced by IL-17 and IFNγ, cytokines involved in the pathogenesis of psoriasis." (PMID 40461723, 2025). "When we analyzed the differences in the cell response to cytokine stimulation (IL17, IFNγ, TNFα—a cocktail mimicking the cytokine background in psoriasis), we observed that the average level of gene expression alterations appeared to be less prominent in the knockdown cells." (PMID 38674130, 2024). "The cytokines they secrete, especially interferon-gamma, IL-1, IL-17, and IL-22, may play a vital role in the pathogenesis of psoriasis de novo or exacerbation." (PMID 38388337, 2024). "IFNγ is another relevant cytokine in the physiopathology of psoriasis." (PMID 37631384, 2023). "Psoriasis is characterized by the Th1 and Th17 polarization of the adaptive immune response, with keratinocytes being activated mainly by the mediators such as interferon gamma (IFN-γ), TNFa, IL-2, and IL-17." (PMID 36830855, 2023). "Interferon gamma (IFN-γ)-producing T cells are also increased in psoriasis." (PMID 37964882, 2023). "In addition, CD8+CD103+ TRM cells can be further classified as two subtypes: CD49a-IL-17A+ and CD49a+IFNγ+, assumedly related to psoriasis and vitiligo, respectively." (PMID 37942312, 2023). "It has therefore been observed that lymphocytes and their cytokines, especially interferon (IFNγ) and interleukin 17 (IL-17), affect other cells, leading to chronic inflammation and characteristic symptoms, such as skin plaques in psoriasis or arthrosis and limited mobility in psoriatic arthritis." (PMID 36292991, 2022). "Previously, our group has demonstrated that apremilast, a phosphodiesterase 4 inhibitor successfully used for the treatment of the disorder, increases IL-10 producing regulatory B cells and decreases IFNγ and IL-17 producing pro inflammatory T subsets in psoriasis and psoriatic arthritis patients." (PMID 35925616, 2022).